COXFA4L2 (cytochrome c oxidase hypoxia associated subunit FA4L2)
Description:
Mitochondrial protein that plays a regulatory role in cellular metabolism, particularly under hypoxic conditions. Downregulates mitochondrial respiratory chain complex I activity under hypoxia, reduces oxygen consumption and ROS and helps cells adapt by switching to glycolysis.
Synonyms: NUOMS; NDUFA4L2; FLJ26118; MISTRH
Tractability: Small molecule: an approved drug acts on it.
Gene: Protein-coding gene on chromosome 12 (57,234,903 to 57,240,715, reverse strand). Ensembl gene ENSG00000185633.
Subcellular location: Mitochondrion inner membrane
Subcellular location (Human Protein Atlas): Mitochondria
Gene Ontology:
Molecular function: enzyme inhibitor activity
Biological process: cellular response to hypoxia; negative regulation of mitochondrial electron transport, NADH to ubiquinone; response to hypoxia; negative regulation of reactive oxygen species biosynthetic process
Cellular component: mitochondrion; mitochondrial inner membrane
Genetic constraint (gnomAD): Loss-of-function variants: 14 observed, 11.23 expected, observed/expected ratio (o/e) 1.25, 90% interval 0.82 to 1.82. The upper end of that interval is the gene's LOEUF score, 1.82, which puts it in group 6 of 6, group 1 being the genes least tolerant of losing a copy. Missense variants: 129 observed, 104.93 expected, observed/expected ratio (o/e) 1.23, 90% interval 1.07 to 1.42. Synonymous variants: 43 observed, 38.7 expected, observed/expected ratio (o/e) 1.11, 90% interval 0.87 to 1.43.
Homologues: Orthologues: chimpanzee NDUFA4L2 (100% identical), macaque NDUFA4L2 (97% identical), mouse Ndufa4l2 (94% identical), rat Ndufa4l2 (94% identical), dog NDUFA4L2 (92% identical), guinea pig NDUFA4L2 (92% identical), rabbit NDUFA4L2 (92% identical), pig NDUFA4L2 (79% identical), zebrafish ndufa4l2a (55% identical), zebrafish ndufa4l2b (41% identical). Paralogues in human: COXFA4 (60% identical), COXFA4L3 (23% identical).
Diseases named in the same sentence as COXFA4L2 in open-access papers:
COXFA4L2 is named in the same sentence as 35 diseases in open-access papers, as found by Europe PMC text mining. Sharing a sentence is not in itself a finding about the gene and the disease.
COXFA4L2 shares sentences with these, for which no sentence is quoted: tumor (39 papers); cancer (31); clear cell renal cell carcinoma (13); hepatocellular carcinoma (7); colorectal cancer (5); kidney cancer (4); breast carcinoma (3); lung carcinoma (3); non-small cell lung carcinoma (3); renal carcinoma (3); glioblastoma (2); glioma (2); hereditary clear cell renal cell carcinoma (2); intervertebral disc degeneration (2); liver cancer (2); osteosarcoma (2); pulmonary arterial hypertension (2); Alzheimer disease (1); bladder cancer (1); cardiomyopathy (1); cholestasis (1); Cognitive impairment (1); colon cancer (1); disc degeneration (1); experimental autoimmune encephalomyelitis (1); gastric adenocarcinoma (1); Leigh syndrome (1); neuroblastoma (1); Niemann-Pick disease, type C1 (1); Obesity (1).
A further 5 diseases each share a sentence with COXFA4L2 in 1 paper.